BRCA1 (BRCA1 DNA repair associated)
Diseases named in the same sentence as BRCA1 in open-access papers (continued):
Sharing a sentence is not in itself a finding about the gene and the disease.
cancer (continued). "A total of 99 (63.5%) females were unaffected and underwent genetic testing because of a known familial BRCA1 or BRCA2 PV, whereas 57 (36.5%) had a cancer diagnosis; 51 (32.7%) had BC and 8 (5.1%) had OC." (PMID 37887578, 2023). "In major studies, 18 target genes such as BRCA1,BRCA2, and PALB2 were reported as biomarkers for cancer progression and development." (PMID 39430039, 2023). "Currently, PARPi are being developed to target not only BRCA1/2defective HBOC, but also other types of cancer that harbor HRD26." (PMID 37165001, 2023). "Among the four associated genes without or very limited prior evidence in cancer pathophysiology is the single-gene locus spanning gene ABRAXAS1—a promising candidate gene for further follow-up owing to its close interactions with protein BRCA1 and its role in DNA damage repair." (PMID 36703164, 2023). "Normal cells are repaired when damaged through HR, but cancer is fatal when PARP-1 is suppressed because the important proteins for HR, BRCA1 and BRCA2, are broken." (PMID 36902170, 2023). "We identified 86 outcomes studies on BRCA1/2m, HRRm, and HRD positivity and OS in our systematic review and meta-analysis across types of cancer." (PMID 35909902, 2022). "However, the role and mechanism of BRCA1 in cancer cell metabolism remain unclear." (PMID 36193432, 2022). "Of the 33 cancer types, BRCA cancer had total levels of BRCA1/2 and BRCAness gene promoter hypermethylation of 14.244 and OV cancer had 13.926." (PMID 36497135, 2022). "Median cancer worry level before surgery (RRSO or RRS) was 14 (interquartile range (IQR) 12; 16) for BRCA1-PV and 14 (IQR 12; 18) for BRCA2-PV carriers." (PMID 34997316, 2022). "Beyond BRCA1/2, carriers also have a stronger family history of BRCA‐related cancers (p value = .006)." (PMID 35608067, 2022). "Polθ inhibition boosts the effect of PARPi by exerting a synthetically lethal action on BRCA1- and BRCA2-mutant cancer cells." (PMID 36613762, 2022). "It has been demonstrated that reversion mutations restoring the native reading frame of the genes can occur in BRCA1-, BRCA2-, PALB2-, RAD51C-, or RAD51D-mutant cancers." (PMID 35326571, 2022). "This large-scale registry-based case-control study analyzed BRCA1 and BRCA2 in 63 828 patients with 14 cancer types and 37 086 controls." (PMID 35420638, 2022). "This study deciphered the BRCA1/2 variant profile, including LGR, in a large population of 56126 pan-cancer patients from the Chinese mainland; the largest Chinese cohort analyzed using NGS for BRCA1/2 LGR cancers to date." (PMID 36147908, 2022). "Theoretically, mosaicism for BRCA1 may not give rise to risk equivalence of constitutional carriers and there is likely ascertainment bias in the few reported mosaic cases in women with young-onset cancer." (PMID 36068545, 2022). "While the provision of preventative care for the management of hereditary cancer risks is still relatively novel, the findings from this study suggest that the perceived quality and availability of care may play a role in the adjustment experiences of the BRCA1/2 population." (PMID 35933387, 2022). "In this report we did a pan-cancer analysis using data reported on the Catalogue of Somatic Mutations in Cancers (COSMIC) to identify double mutants between RAD52 and BRCA1, BRCA2 or PALB2 that occur in cancer cells." (PMID 36107942, 2022). "Three months post-surgery, median cancer worry declined to 13 (IQR 10; 14) for BRCA1-PV and to 12 (IQR 10; 16) for BRCA2-PV carriers." (PMID 34997316, 2022). "There were no significant changes in gene expression levels for the seven other cancer genes (ABCC1, ALK1, BRCA1, DHRS2/HEP27, EGFR, ERBB2, and ERCC1)." (PMID 35743133, 2022). "Among the interface genes in the Her2+_TNBC module, the known cancer-related genes are mostly DNA repair genes, such as BARD1, BRIP1, BRCA1, BRCA2, FANCA, FANCC, FANCD2, and FEN1." (PMID 35992864, 2022).
cancer (continued). "In fact, BRCA1-mutated (and HR-deficient) OC cells rely on PARP for DNA repair and survival and our results suggest that high XIAP expression may function to maximise PARP levels in these cancer cells, since XIAP inhibits the caspases that cleave and degrade PARP." (PMID 35501389, 2022). "Although in the clinics, PARP inhibitors have been used to treat cancers with DSB repair defects, such as BRCA1 and BRCA2 defect cancers, the drug resistance to PARP inhibitors is now a major problem facing the clinic." (PMID 35883563, 2022). "In this report, we describe the molecular regulations of the expression of the breast cancer oncogenes HER2, BRCA1, and BRCA2 and the role of iNOS expression in those regulations." (PMID 35740092, 2022). "We also evaluated the expression of BRCA-1 and RAD51, molecules involved in HR, an error-free DNA repairing pathway, which is essential for cancer cell integrity." (PMID 36012375, 2022). "After that, we compared the expression of cancer biomarkers ATM, BRCA1, PDCD1, and EGFR gene in the two groups." (PMID 36226174, 2022). "This information can potentially improve genetic testing of BRCA1 and BRCA2 for various cancer types for Asian countries and encourage similar research in other countries." (PMID 35420638, 2022). "Upregulation of Pgp expression is considered a mechanism of resistance in BRCA1 and BRCA2 mutant cancers treated with PARPIs." (PMID 35785170, 2022). "BRCA1 and BRCA2 are tumor suppressor genes with a key role in DNA repair processes and cell-cycle checkpoints, in response to DNA damage, whose mutations may induce genomic instability, cell-cycle dysregulation, and accumulation of other mutations, thus increasing the risk of cancer development." (PMID 36359251, 2022). "Polθ is becoming a new target in cancer research because it demonstrates numerous synthetically lethal interactions with other DNA repair mechanisms, e.g., those involving PARP1, BRCA1/2, DNA-PK, ATR." (PMID 36613762, 2022). "Among other cancer types, we observed four prostate samples with high HRD scores from both classifiers containing biallelic inactivation in BRCA1/2 and one biliary sample with a germline BRCA1 alteration where both HRD scores were above default." (PMID 35783256, 2022). "To assess the importance of promoter methylation in the evaluation of HRD classifiers' performance, we removed the methylation data of BRCA1/RAD51C promoters in breast and ovarian the only cancer types for which methylation data were available." (PMID 35783256, 2022). "Therefore, it is thought that BRCA1/2 deficient or HR-deficient cancer cells are selectively sensitive to PARPi because the collapsed replication forks are not properly repaired in HR-deficient cancer cells." (PMID 35805011, 2022). "We have claimed from the overall studies that α-hederin, andrographolide, apigenin, asiatic acid, auricularic acid, and sinularin will be the best conformer for BRCA1, BRCA2, and MDR1-conduced cancer for the future researchers." (PMID 35837379, 2022). "Twelve months post-surgery, median cancer worry was 12 (IQR 10; 15) for both BRCA1-PV and BRCA2-PV carriers." (PMID 34997316, 2022). "Nevertheless, α-hederin, andrographolide, apigenin, asiatic acid, auricularic acid, and sinularin successfully docked with BRCA1, BRCA2, and MDR1 proteins as these compounds have the activity for inhibiting cancer." (PMID 35837379, 2022). "Generally, tumor suppressor genes such as BRCA1, RB, and APC lose function through deletions or truncating variations in cancer cells." (PMID 36045334, 2022). "In 1998, Myriad Genetics was awarded a patent for both BRCA1 and BRCA2 genes and began offering commercial testing for these hereditary forms of cancer." (PMID 35626055, 2022).
cancer (continued). "Among 10,480 cancer patients, we identified 20 individuals with HCC diagnosis of which two were PV carriers in established CPGs (BRCA1 and CHEK2)." (PMID 36612198, 2022). "Future studies should attempt to identify variants that influence gene expression and post-transcription modifications to improve our understanding of BRCA1 and BRCA2, as well as their related cancers." (PMID 35087763, 2021). "In this setting, NGS, a robust and highly sensitive technology, provides clinicians with the opportunity to comprehensively evaluate BRCA1/2 molecular status in both HGSOC and other types of cancer." (PMID 34946865, 2021). "Some of the other enriched transcription factors include MYB, BRCA1, STAT1 and ETV4 which are upregulated in majority of the cancer types." (PMID 34728699, 2021). "Among 1,627 participants (95.2% with cancer), we detected 236 (14.5%) BRCA PVs; 160 BRCA1 (31% CNVs); 76 BRCA2 PV frequency varied by country: 26% Brazil, 9% Colombia, 13% Peru, and 17% Mexico." (PMID 34413315, 2021). "Three clinically significant and highly studied genes were selected as target genes for each cancer type: HERE2, MYBL2, and MMP11 for BRCA and NOTCH2, BRCA1, and PDC for COAD." (PMID 34422018, 2021). "This translational work is typically designed to investigate clinically relevant subsets of cancer, such as platinum sensitive or platinum resistant tumors, or in PDX models with specific tumor genotypes such as BRCA1- or BRCA2-mutant models." (PMID 33850213, 2021). "As somatic events in BRCA1 or BRCA2, genomic reversion is known as a mechanism for acquiring resistance to PARPi or platinum chemotherapy in cancer cells." (PMID 35008774, 2021). "Anti-cancer therapy based on the personalized ATM and BRCA1 expression can probably improve the outcome of HNC patients." (PMID 34068585, 2021). "The synthetic lethality interaction is observed in the clinic, in tumours harbouring somatic biallelic inactivation in BRCA1/2, leading to approval of PARP inhibitors in BRCA1/2 cancers." (PMID 34067960, 2021). "Within the genes BRCA1 or BRCA2, cancer cluster regions are genetic regions containing a disproportion amount of gene mutations." (PMID 34711195, 2021). "Given the function of BRCA1 or BRCA2 in HR repair and maintaining replication fork stability, multiple mechanisms are involved in resistance to PARP inhibitors and cancer cell survival." (PMID 34063568, 2021). "For example, BRCA1 and BRCA2 are mostly specific to a small set of cancer types such as breast and ovarian cancer, and are highly enriched in Ashkenazi Jews2." (PMID 34290314, 2021). "A range of genes encoding proteins involved in homologous recombination DNA repair (BRCA1/2, RAD51, UBE2T/FANC2, CHEK1, PCNA, TOP2A) is also upregulated, possibly reflecting an increased requirement in cancer cells subject to replication stress." (PMID 34885146, 2021). "The present analysis suggests that, instead, upregulation of BRCA1 and BRCA2 is prevalent, potentially in a different subset of cancers." (PMID 34885146, 2021). "Together, these results suggest that modulation by BRCA1+/− iMSCs, which secrete high levels of POSTN, conferred enhanced self-renewal ability on 4T1 cancer cells, which is one of the characteristics of cancer stem cells." (PMID 33513753, 2021). "HMGA2 is regulated by the BRCA1/ZNF350/CtIP repressor complex, and miRNA-182 can prevent BRCA1 translation and increase HMGA2 expression in cancer cells." (PMID 34072941, 2021). "The results were further validated in the GTEX database; the correlation between HSP90AA1 and BRCA1 and CDK1 was only observed in cancer patients." (PMID 35095481, 2021).
cancer (continued). "PPI of BAP1 with BRCA1 was central to understanding the role of BAP1 in growth-control pathways and cancer; BAP1 was suggested to play a role in BRCA1 stabilization." (PMID 33916178, 2021). "There were fewer BRCA1/2 carriers at NWH than MGH and UPenn, which is partly expected, as NWH is a community hospital, whereas MGH and UPenn have large cancer genetics clinics." (PMID 35008209, 2021). "We also demonstrated that inhibition of ATM kinase induced apoptosis signaling and potentiated cisplatin-induced cytotoxicity in cancer cells, which implies a potential treatment strategy for the HNC patients with low ATM and BRCA1 expression." (PMID 34068585, 2021). "The results revealed considerable differences in BRCA1- and BRCA2-dependent transcriptome landscapes in the studied cancers." (PMID 33525353, 2021). "Overall, the six genes that had PVs with prevalences greater than one percent for any patient cohort (ATM, BRCA1, BRCA2, CHEK2, CDKN2A and FANCA) comprise a heterogenous group of genes that reflect the complexity of this cancer." (PMID 34255164, 2021). "Patients were divided according to the timing of BRCA1/2 PVrecognition, before (BRCA-preDx awareness, N = 62) or after (BRCA-postDx awareness group, N = 284) cancer diagnosis." (PMID 34540661, 2021). "Therefore, these validated genes are potential key hub genes and critical regulatory factors in BRCA1/2-MUT BC, which could represent new prognostic or diagnostic biomarkers and provide novel insights into the mechanisms of BRCA1/2 mutations in cancer development." (PMID 34733851, 2021). "Furthermore, no SNVs were detected in the cancer-predisposing genes BRCA1/2." (PMID 34205964, 2021). "This chromosomal region contains several genes connected to cancers including EME1, BRCA1, ERBB2, NF1, RAD51C, BRIP1, BIRC5 and PPM1D." (PMID 34885154, 2021). "Therefore, BRCA1- and TP53BP1-deficient cancer cells may be eliminated by SSA/RAD52 inhibition." (PMID 33671579, 2021). "The age at diagnosis of cancers other than breast and prostate was 65 years in BRCA2 carriers versus 67 years in BRCA1 carriers." (PMID 34575694, 2021). "Therefore, it is essential to identify the overlap between participants of the both studies by linking the two data sources, which will allow setting up studies evaluating simultaneously genetic and non-genetic factors modifying cancer risk of carriers of a BRCA1 or BRCA2 mutation." (PMID 34325649, 2021). "We align the sequence pairs for the coding sequences of the genes of BRCA1, ELK1, and CCDC91, which are related to cancer incidence –." (PMID 35402983, 2021). "Mean age at cancer diagnosis in each family was 47.0 and 54.0 years for BC and OC, respectively, in female relatives of VEO cancer BRCA1 families, and was 46.8 and 55.5 years, respectively for BC and OC in no VEO cancer BRCA1 families." (PMID 34356116, 2021). "Different regulatory elements drive the hypoxia-induced repression of BRCA1 and the activation of NBR2 in cancer cells." (PMID 34926299, 2021). "We have also discussed potential biomarkers involved in pathways that are differentially affected or modified during the onset of HPV-related cancers, such as Akt, mTOR, miRNAs, TNF-α, TGF-β, BRCA1, and FANCD2." (PMID 33668730, 2021). "Accordingly, tumors with disrupted HR or NHEJ pathways, including BRCA1/2, rely on POLQ activity for DSB repair, and are sensitive to POLQ inhibition, PARP inhibition or cancer therapies introducing DSBs." (PMID 32885167, 2020). "Although the ABCD test cannot explain the BRCA status of non-BRCA1/2 tumors, it is a rapid and precise method that directly evaluates the PARP inhibitor sensitivity of cancers harboring BRCA2 VUSs." (PMID 32444794, 2020). "BRCA1/BRCA2 are exceptions with an OR > 10 for BRCA, but also show more moderate OR for other cancer types." (PMID 32471518, 2020). "Lastly, we analyzed BRCA1 and BRCA2 mRNA because of their implications in cancer and DNA repair mechanisms." (PMID 32610620, 2020).
cancer (continued). "Current guidelines recommend BRCA1 and BRCA2 genetic testing for individuals with a personal or family history of certain cancers." (PMID 32376921, 2020). "The relationship between the tumor-suppressive genes BReast CAncer type 1 and Type 2 (BRCA1/2) and hereditary breast and ovarian cancer syndrome (HBOC) revolutionized clinical cancer genetics." (PMID 32605126, 2020). "Predicted genes targeted by dysregulated oncomiRs or tumor suppressor miRNAs were mainly involved in cell cycle regulators such as CAPRIN1, CDC42, PTEN, IGF1R, BRCA1 and CD28, thereby controlling cancer dormancy." (PMID 33374139, 2020). "Much of the previous research reporting on psychosocial outcomes after genetic testing for BRCA1 and BRCA2 has enrolled women from academic cancer genetics clinics." (PMID 32393849, 2020). "With loss of BRCA1, HOTAIR competitively interacts with EZH2 via similar binding site to BRCA1, culminating in hypermethylation of H3K27me3 and PRC2 occupancy of the corresponding target sites in the breast luminal epithelial cancer cells." (PMID 32245498, 2020). "This is true especially for cancers with a strong hereditary component such as FBC, in which several studies have investigated the role of genes other than BRCA1/2." (PMID 32365798, 2020). "Although BRCA1m are highly heterogeneous and therefore difficult to target, BRCA1 gene's synthetic lethal pair, PARP1, is conserved in BRCA1m cancer cells." (PMID 31989039, 2020). "Even in the setting of germline BRCA1/BRCA2, which is present in all breast cells, solitary cancers or cancers arising at only several foci occur." (PMID 33196707, 2020). "There are important uncertainties and differences in strength of evidence and differential effects for BRCA1 and BRCA2 with regard to these and other possible additional cancer risks." (PMID 32655641, 2020). "Moreover, no individual BRCA1/2-associated cancer type demonstrated an association with high GS; PC (OR: 1.17 [95% CI: 0.69–1.97], p = 0.567), BrC (OR: 0.92 [95% CI: 0.48–1.76], p = 0.808), PaC (OR: 0.55 [95% CI: 0.24–1.25], p = 0.146), and OvC (OR: 0.54 [95% CI: 0.11–2.69], p = 0.443)." (PMID 33351846, 2020). "For instance, the dysfunction of BRCA1/2 and/or BARD1 sensitizes cancer cells to chromosomal instability and subsequent apoptosis induced by inhibition of poly (ADP‐ribose) polymerase (PARP) enzymatic activity." (PMID 32730698, 2020). "While we found several cancer signaling pathways enriched in PRMT5 inhibited cells, we also observed a depletion of pathways involved in various DNA repair pathways, such as BRCA1, nucleotide excision repair (NER) and ATM signaling." (PMID 32555249, 2020). "LOH of BRCA1/2, RAD51C or PALB2 was also found as a monoallelic event, mainly in ovarian (47%) and breast (49%) cancer patients." (PMID 33149131, 2020). "However, this hypothesis seems contradictory to the observation in BRCA1 mutant human cancers, where BRCA1 mutations do not compromise cell proliferation." (PMID 32257107, 2020). "In BRCA1‐proficient TNBC cells, we observed the same result—that elevated wild‐type KLF4 drastically promotes cancer cell survival in the presence of olaparib, whereas little effect was observed for expression of the PARylation‐deficient KLF4 mutant." (PMID 33231937, 2020).